ASPN (asporin)
Diseases named in the same sentence as ASPN in open-access papers (continued):
Sharing a sentence is not in itself a finding about the gene and the disease.
tumor (continued). "LC-MSCs promote tumor angiogenesis by secreting various pro-angiogenic factors (ASPN, Clusterin, vascular endothelial growth factor (VEGF), IL-8, Ang and PDGF-BB)." (PMID 35842634, 2022). "In contrast to the results obtained by other researchers, the results of our study showed a significant increase in the expression level of the ASPN gene in fibroblasts (|logFC|≥1 and pvalue<0.05) after cultivation with 3 different tumor cell lines." (PMID 36263012, 2022). "Further studies verify that ASPN expression is low in non-tumor tissues, including breast tissue, on the contrary to DCN and BGN, which present high expression levels in normal tissues." (PMID 36358747, 2022). "This dataset showed that the high-level Z-scores of asporin were positively correlated with PTC patients with larger tumor classification (P < 0.001), LNM (P < 0.001), high AJCC staging (P < 0.001), and BRAFV600E mutation (P < 0.001)." (PMID 35600399, 2022). "Studies support that ASPN has key roles in modifying the tumor microenvironment and promoting tumor progression to metastasis." (PMID 33600062, 2021). "The expression of ASPN was positively correlated with tumor stage (p = 0.047) and lymph node metastasis (p = 0.008)." (PMID 34379688, 2021). "A significant increase in expression of ASPN in tumor tissue vs. normal tissue was observed in both TCGA and our patient cohort." (PMID 34379688, 2021). "The TCGA-STAD cohort, revealed a significantly elevated ASPN gene expression in GC tissues vs matched adjacent non-tumor tissues, while reduced expression of DCN was found in cancer tissues vs normal non-tumor tissues." (PMID 34379688, 2021). "Our study uncovers ASPN as a GC-promoting gene and DCN as tumor suppressor, suggesting that ASPN can act as a prognostic marker in GC." (PMID 34379688, 2021). "Involvement of TGFβ in the regulation of EMT phenotype, collagen synthesis and angiogenesis were assessed in aggressive tumor tissues with high ASPN expression and low DCN expression." (PMID 34379688, 2021). "In OT cohort tumor samples, we found up regulation of ASPN in 26 out of 42 samples (61.9%), while DCN was down regulated in 22 out of 42 samples (52.4%)." (PMID 34379688, 2021). "ASPN expression in CAFs has been shown to impact the tumor microenvironment, to enhance cellular invasion, and to promote metastatic progression." (PMID 33600062, 2021). "Here, we investigated the complex interplay of asporin, decorin and their interaction with TGFβ in GC tumor and corresponding normal tissues." (PMID 34379688, 2021). "Expression for MMP3 (t = 4.884, p < 0.0001), SLC2A1 (t = 3.703, p = 0.0006), DDK3 (t = 3.981, p = 0.0003), POSTN (t = 2.061, p = 0.0455), RBP4 (t = 3.048, p = 0.004) and ASPN (t = 2.733, p = 0.0091) was confirmed to be higher in the tumor tissues." (PMID 32854182, 2020). "ASPN belongs to a family of small leucine-rich proteoglycans, and it is known as a major component of tumor stroma and its aberrant expression has been found in multiple tumors." (PMID 30065754, 2018). "As asporin belongs to secreted proteins, regulation of its expression both in CAFs and cancer cell is relevant for alteration of the tumor microenvironment." (PMID 27409832, 2016). "Asporin promoted the migration and invasion of the tumor cells partially through an EGFR/Src/cortactin- signaling pathway." (PMID 27705916, 2016). "With respect to these contradictory results, the role of asporin in cancer progression and the tumor microenvironment deserves further investigation." (PMID 27409832, 2016). "This is in agreement with our key findings that tumor cells with known genetic differences as well as distinct tumorigenic and metastatic potentials have a heterogeneous ability to induce or inhibit asporin expression in stromal fibroblasts." (PMID 26327350, 2015). "The evaluation of tumor stemness, using two different and independent signatures, showed that asporin-expressing tumors had a significantly lower percentage of stem cells." (PMID 26327350, 2015).
tumor (continued). "Following tumor resection, animals with tumors expressing asporin develop fewer and much smaller metastatic deposits in the lungs." (PMID 26327350, 2015). "In this cohort the tumor growth was followed for a longer period of time (control mice 9 wk, asporin 12 wk), highlighting an overall 3-wk delay of tumor growth in asporin-expressing mice." (PMID 26327350, 2015). "ASPN regulates several signalling pathways in the tumour microenvironment (TME)." (PMID 40566602, 2025). "Moreover, ASPN promotes invasion by neighboring tumor cells through paracrine effects mediated by activation of the CD44-Rac1 axis." (PMID 40075643, 2025). "ASPN: Asporin—A protein that regulates collagen and tumor invasion." (PMID 40075643, 2025). "The presented results and earlier findings indicate that a high expression of ASPN in ovarian stromal cells could be an indicative marker gene of tumor progression in ovarian stroma." (PMID 39342193, 2024). "Asporin, one of the connective tissue proteins, has already shown its major role in cancer progression, restricting mesenchymal stromal cell differentiation, altering the tumor microenvironment, and driving therefore a metastatic progression." (PMID 37108678, 2023). "The extracellular matrix protein asporin (ASPN) has been shown to promote cell migration and invasion and may be a key molecule in facilitating tumor spreading." (PMID 35631574, 2022). "ASPN also plays dual roles in breast cancer with both pro‐ and anti‐tumor effects reported." (PMID 34379869, 2022). "Therefore, elevated asporin expression in tumorous tissue was found to correlate positively with a poorer prognosis, thus, also implicating asporin as a novel candidate prognostic biomarker." (PMID 35600399, 2022). "Asporin (ASPN), an extracellular matrix protein, is a member of a family of small leucine-rich proteoglycans that has been found to play an important role in collagenogenic fibril production, signal transduction and tumour growth." (PMID 36394011, 2022). "Inflammatory cytokines, ASPN, and downstream molecules were successively transmitted from fibroblast to fibroblast via the generation of CEFs, ultimately resulting in cancer cell spreading and tumor dissemination." (PMID 34379869, 2022). "Since ASPN regulates GC metastasis through activation of EGFR and the ERK-CD44/MMP-2 pathway, it perhaps favourably associates with TGFB1 and activates the signaling pathway to promote tumor growth and progression." (PMID 34379688, 2021). "However, NT5E+ cells, TNC+ cells, and PDGFRβ+ cells shifted from ASPN− to ASPN+ in the cribriform tumor microenvironment." (PMID 33600062, 2021). "Furthermore, patients with stage 3 and stage 4 tumor showed significantly higher ASPN expression than patients with stage 1 tumor (p<0.001 and p<0.001, respectively)." (PMID 34379688, 2021). "In this study, fibroblast subtypes enriched in the cribriform tumor microenvironment were ASPN+." (PMID 33600062, 2021). "ASPN expression was confirmed to be up regulated in the majority of tumor samples." (PMID 34379688, 2021). "Interestingly, asporin, a factor secreted by MSCs following cellular interactions within the tumor microenvironment, alters the tumor microenvironment and inhibits MSC differentiation to drive metastatic progression through CD49d/CD29 signaling." (PMID 33299638, 2020). "Similarly, asporin, a factor secreted by MSCs following cellular interactions within the tumor microenvironment, altered the tumor microenvironment and inhibited MSC differentiation to drive metastatic progression through CD49d/CD29 signaling." (PMID 33330442, 2020). "Finally, due to the function of asporin as a tumor suppressor gene and oncogene in different types of cancer, the exact molecular mechanisms of its dual role in different tumor microenvironments remain to be elucidated." (PMID 31608236, 2019).
tumor (continued). "Furthermore, asporin is also positively or negatively correlated with tumor proliferation, migration, invasion, and patient prognosis through its regulation of different signaling pathways, including the TGF-β, EGFR, and CD44 pathways." (PMID 31608236, 2019). "Recently, asporin expression was also shown to be dysregulated in tumor tissues and positively or negatively correlated with tumor proliferation, migration, invasion, and patient prognosis by regulating different signaling pathways, including the TGF-β, EGFR, and CD44 pathway." (PMID 31608236, 2019). "This diminishing asporin expression may underestimate asporin’s effect on tumor growth and metastasis in vivo." (PMID 26327350, 2015). "Therefore, we next sought to engraft asporin-overexpressing cancer cells that would maintain constant asporin expression in the tumor." (PMID 26327350, 2015). "We thus sought to verify whether asporin expression remained constant in the tumor during the present experiments." (PMID 26327350, 2015). "ASPN may therefore be a key molecule in facilitating tumor spreading and T‐cell suppression." (PMID 34379869, 2022). "In our study, we showed that over expression of ASPN in tumor tissue is correlated with high expression of mesenchymal proteins such as N-cadherin, fibronectin, and low expression of the epithelial marker protein—E-cadherin, indicates metastasis in tumor tissues." (PMID 34379688, 2021). "In the murine model of TNBC, asporin overexpression CAFs could significantly reduce tumor growth." (PMID 33614646, 2021). "Deeper investigations into commonly overexpressed genes, including ASPN, STK3 and BAMBI, via immunohistochemistry revealed novel findings on cellular protein expression in canine tumours." (PMID 40566602, 2025). "Most of the TMEM119+ FIBs appeared to be positioned peripherally and juxtaposed to KRT14+ tumor nests, to a greater extent than those observed for CLIC2+ and CEMIP+ FIBs or sparse ASPN+ FIBs." (PMID 35687691, 2022). "The expression of asporin (ASPN), an extracellular secreted protein with oncogenic potential is elevated in the tumor stroma of PCa patients and, based on this observation, it has been proposed to be used as a CAF marker." (PMID 34071280, 2021). "This study reveals the possible role of ASPN and DCN in tumor progression and provides evidence that both ASPN and DCN can serve as novel prognostic biomarkers of GC." (PMID 34379688, 2021). "COL3A1, COL1A2, COL15A1, ASPN, and MXRA5 were higher expressed in tumor samples, while OGN was lower expressed." (PMID 32300359, 2020). "Asporin, a member of the small leucine-rich proteoglycans (SLRP) family, can act as a tumor promoter or a tumor suppressor in BC." (PMID 33371274, 2020). "We showed extracellular matrix modifications of the tumor and upregulation of factors generally secreted by CAFs such as CXCL12, ASPN and OLFML3." (PMID 26437222, 2015). "Protein-protein interaction analysis identified four hub genes-ASPN, SELE, ACKR1 and ABCB1-integrating ECM remodelling, endothelial-immune modulation and xenobiotic transport, reinforcing an immune-attenuated, metabolically adapted tumour landscape." (PMID 42194092, 2026). "ASPN showed elevated expression in canine OSA tumours compared to non-malignant counterparts (n = four matched samples; p = 0.0091)." (PMID 40566602, 2025). "In addition, the ACTA2, ASPN, PDGFRB, PDPN, COL12A1, EMILIN1, and CDH11 genes were upregulated in CAFs of several tumor types." (PMID 36263012, 2022). "Moreover, the expression of ACTA2, ASPN and COL11A1 genes are reduced in fibroblasts after cultivation with tumor cells." (PMID 36263012, 2022). "Adjacent normal epithelium showed weak or no staining (N = 4), whilst the majority of tumor epithelium showed increased ASPN expression (N = 8)." (PMID 34379688, 2021). "ASPN is highly expressed in patient tumor tissues compared to normal tissues, whereas DCN showed opposite pattern of gene expression." (PMID 34379688, 2021).
tumor (continued). "While the overall expression of NT5E, TNC, and PDGFRβ did not change in the tumor microenvironment, ASPN expression was altered in these cells." (PMID 33600062, 2021). "Co-IP assays were performed to assess whether ASPN and DCN could physically interact with TGFβ in GC tumor and normal tissue." (PMID 34379688, 2021). "In contrast asporin and biglycan was not expressed in normal tissues but was found to be expressed in the tumor stroma." (PMID 24634138, 2014). "Furthermore, it is not known if increased ASPN expression in the tumor microenvironment is due to increased ASPN+ cells, possibly to increased ASPN expression per cell, or a combination of both." (PMID 33600062, 2021). "However, a recent study indicated that the expression of only decorin, but not the other related SLPRs such as asporin and biglycan, varied between tumor and normal tissues." (PMID 26379028, 2015). "Assessment of asporin expression and patient outcome (n = 60; 10-y follow-up) shows that low protein levels in the primary breast lesion significantly delineate patients with bad outcome regardless of the tumor HR status (area under the curve = 0.87; 95% CI 0.78–0.96; p = 0.0001)." (PMID 26327350, 2015). "OCUM‐12‐CM did not induce ASPN, inflammatory cytokines, HIF‐1α, IDO‐1, or KYNU expression in NFs in vitro, suggesting changes to the tumor would reflect the effects of the coinjected CEFs." (PMID 34379869, 2022).
cancer (50 papers, 2007 to 2025). A tumor composed of atypical neoplastic, often pleomorphic cells that invade other tissues. "The underlying mechanism includes the ASPN-mediated activation of Rac1 in both CAFs and cancer cells through its interaction with CD44." (PMID 36358747, 2022). "In line with other studies, we have confirmed asporin expression by RNA scope in situ hybridization in cancer associated fibroblasts." (PMID 27409832, 2016). "Subsequently, in a variety of cancers, ASPN can either cause or inhibit cancer through EMT." (PMID 36595867, 2022). "However, asporin has been repeatedly reported to be expressed by cancer associated fibroblasts (CAFs) or other stromal cell types." (PMID 27409832, 2016). "Prior studies have shown that ASPN+ CAFs induce cancer cell migration, but the mechanisms for this are not fully understood." (PMID 40857406, 2025). "Prior studies have shown that ASPN can support cancer metastasis by modulating TGF-β signaling and ECM organization." (PMID 40868045, 2025). "Thirdly, ASPN, coding for asporin, is an extracellular matrix proteoglycan involved in cell development and cellular signaling but also, in the scope of cancer, in resistance to growth inhibitors, inhibition of apoptosis, and promotion of cancer metastasis." (PMID 40076457, 2025). "ASPN can be expressed by CAFs, promoting cancer cell invasion and metastasis, whilst the knockdown of ASPN in CAFs reduced fibroblast and gastric cell invasion in vivo." (PMID 40566602, 2025). "CAFs play important roles in the progression, metastatic spread and drug resistance of OSA, though their secretion of ASPN and its potential impact on tumourigenesis have yet to be investigated in this cancer type, representing an area of future research." (PMID 40566602, 2025). "As a secreted protein, ASPN has been shown to communicate throughout the TME to orchestrate cancer cell migration and metastatic development, yet the mechanisms driving these functions are not well defined." (PMID 40857406, 2025). "Due to the high percentage of canine specimens displaying stromal ASPN (86.67%), combined with the lower scores within subcellular locations in the present study, it may be possible that elevated ASPN secretion levels are via cancer-associated fibroblasts (CAFs) within the TME." (PMID 40566602, 2025). "Our ECM panel for PCC-NOS includes SLRPs like LUM, BGN, PRELP, and ASPN, which exhibit dual functions in cancer." (PMID 39305996, 2024). "Although asporin is upregulated in pancreatic ductal, prostate and breast cancers, it acts as a tumor-suppressor gene in triple-negative breast cancer." (PMID 36765749, 2023). "The most significant cancer-related pathways regulated by asporin are FGF2, TGF-β1, BMP-2, epidermal growth factor receptor (EGFR) and CD44." (PMID 36765749, 2023). "ASPN showed moderate expression in cystitis, moderate-to-high expression in low grade cancer, and high expression in high grade cancer." (PMID 35330118, 2022). "While α‐SMA+ CAFs were observed at the highest density in the cancer core region, where cancer cells compacted, ASPN was mainly expressed in the distal area." (PMID 34379869, 2022). "ASPN overexpression has been shown to lead to cancer progression and enhanced metastasis, and its expression is similar in mesenchymal stromal cells and CAFs." (PMID 35687691, 2022). "Unsupervised principal component analysis with the main cancer invasiveness-enriched genes (ASPN, GLT8D2, OLFML2B, CRISPLD2, ADAM12, POSTN, and PRRX1) allowed for the discrimination of subgroups of BMAL1-dependent CRC patients (p = 9.9 × 10−4)." (PMID 34065633, 2021). "While low in benign adjacent stroma, ENG+ASPN+ cells largely accounted for this increase in the cancer‐adjacent stroma." (PMID 33600062, 2021). "This group also found that asporin expression was promoted by TGF-β1 and inhibited by IL-1β in normal breast fibroblasts, as well as cancer-associated fibroblasts (CAFs)." (PMID 31608236, 2019).